IL2 (interleukin 2)
Diseases named in the same sentence as IL2 in open-access papers (continued):
Sharing a sentence is not in itself a finding about the gene and the disease.
metastatic melanoma (continued). "IL2 was approved by FDA for metastatic melanoma patients in 1998, based on the observation that a small proportion of subjects enjoyed durable complete responses." (PMID 33110477, 2020). "Similar efficacy was observed with high-dose IL-2 treatment for metastatic melanoma, where 16% of patients (270 patients total) had an objective response with 17 patients having a complete response and 26 patients experiencing a partial response." (PMID 30842774, 2019). "NK cells can be stimulated with systemic administration of activating cytokines, like interleukin-2 (IL2), as described in patients with renal cell carcinoma and metastatic melanoma." (PMID 31324064, 2019). "Additional evidence was derived from the observation that the combination of adoptive transfer of in-vitro-expanded tumor infiltrating lymphocytes/high-dose IL-2 immunotherapy demonstrated efficacy in the treatment of refractory metastatic melanoma." (PMID 30813267, 2019). "Based on this preclinical data a phase II clinical trial combining IL-2 with RT was conducted in metastatic melanoma." (PMID 31179236, 2019). "Several additional clinical studies examining SABR in combination with IL-2 in metastatic melanoma and renal cell carcinoma are underway." (PMID 31179236, 2019). "It is possible that the low response rate compared to other published clinical trials of TIL therapy for metastatic melanoma was due to the low-dose IL-2 regimen in our protocol; randomized trials would be needed to address this." (PMID 30747243, 2019). "To assess a modified TIL protocol using lower dose IL-2, we performed a single institution phase II protocol in unresectable, metastatic melanoma." (PMID 30747243, 2019). "A pilot study assessing the safety and response rate combination of SBRT followed by a high-dose IL-2 regimen in patients with metastatic melanoma and renal cell carcinoma showed complete response or partial response in 8 out of 12 patients." (PMID 31179236, 2019). "Subsequently, the FDA approved recombinant interleukin-2 (IL-2) for the treatment of metastatic renal cancer and metastatic melanoma in 1992 and 1998, respectively." (PMID 31779642, 2019). "Recombinant interleukin-2 has been shown to eradicate metastatic melanoma or renal cell carcinoma in a small proportion of patients, who are fit enough to tolerate the severe side-effects associated with cytokine treatment." (PMID 31803362, 2019). "Several studies mainly in metastatic melanoma or renal cell carcinoma have been conducted over the last two decades combining IL-2 and various doses and techniques of RT, however, generally with a low efficacy or partial responses." (PMID 31179236, 2019). "For a long period, the only treatments for patients with metastatic melanoma included chemotherapy with dacarbazine and some other agents as well as immunotherapy with high doses of IL-2." (PMID 31028434, 2019). "In fact, since the 1980s high dose IL-2 has been used to treat patients with renal cell carcinoma and metastatic melanoma." (PMID 30842774, 2019). "Infusion of IL-2 in multiple cycles at distinct doses in patients with metastatic melanoma and RCC has led to the first success in cancer immunotherapy, demonstrating that the immune system can completely eradicate tumor cells under certain conditions." (PMID 31703694, 2019). "There are currently 60 institutions in North America with high doses of IL-2 for metastatic melanoma and renal cell carcinoma." (PMID 29980186, 2018). "In the management of metastatic melanoma, Interleukin-2 (IL-2), alone or in combination with chemotherapy or biotherapy, is a standard treatment." (PMID 29492238, 2018). "It was also shown that IL-2 was crucial for the expansion of the transferred lymphocytes ex vivo, as well as for the regression in metastatic melanoma when directly administered." (PMID 29725606, 2018). "High-dose interleukin-2 (HDIL-2) was the first FDA-approved immunotherapy for the treatment of metastatic melanoma in 1998." (PMID 30567529, 2018).
metastatic melanoma (continued). "As a monotherapy, IL-2 has been shown to mediate tumor regression and has been used for treating metastatic renal cell carcinoma and metastatic melanoma." (PMID 29980186, 2018). "Durable responses are consistently observed in a small percentage of patients with metastatic melanoma treated with HD IL-2." (PMID 30053905, 2018). "High-dose recombinant interleukin-2 therapy in patients with metastatic melanoma: long-term survival update." (PMID 30400822, 2018). "IL-2 was identified in 1976 as a T cell growth factor and later approved for treatment of patients with metastatic melanoma and renal cell carcinoma with beneficial results in a subset of patients." (PMID 30619269, 2018). "Infact, a well-studied phenomenon of high-dose IL-2 therapy is peripheral lymphocytosis observed in patients receiving treatment for metastatic melanoma." (PMID 30376886, 2018). "Per the 2017 NCCN guidelines, high dose interleukin-2 (HD IL2) therapy for metastatic melanoma is recommended as second line and recommended as first line for predominant clear cell histology for Stage IV renal cell carcinoma." (PMID 30342473, 2018). "Ninety one patients were identified with metastatic melanoma or RCC who received high dose IL2 therapy." (PMID 30342473, 2018). "Rigors are a significant adverse event during interleukin-2 (IL2) therapy for metastatic melanoma and renal cell carcinoma." (PMID 30342473, 2018). "Durable remissions are observed in a fraction of metastatic melanoma patients treated with high-dose interleukin-2 (HD IL-2)." (PMID 28923120, 2017). "The high dose of IL-2 injection has been used to mediate the regression of metastatic melanomas and renal cell carcinomas." (PMID 27805072, 2017). "Retrospective analyses of metastatic melanoma patients who had been treated with IL-2 demonstrated an ORR of 16% and represented a significant advance in the treatment." (PMID 29276510, 2017). "Considered the first effective cancer immunotherapy, high-dose IL-2 is able to mediate durable responses in a small subset of metastatic melanoma and metastatic renal cancer patients." (PMID 28497796, 2017). "IL-2 has been used for more than two decades in the therapy of metastatic melanoma which, in some of treated patients, resulted in induction of long-lasting remission." (PMID 29219852, 2017). "For example, cytokines such as interleukin-2 (IL-2) have been demonstrated to stimulate the immune system and favourable responses to IL-2 therapy have been demonstrated in patients with metastatic melanoma and renal cell cancer." (PMID 27367731, 2016). "In 1998, the US FDA approved IL-2 for the treatment of metastatic melanoma, based on clinical observations demonstrating sustained remissions in approximately 5–10% of patients." (PMID 27833586, 2016). "High-dose interleukin-2 (IL-2) was approved for the treatment of metastatic melanoma based on data demonstrating sustained remissions in approximately 5%–10% of patients." (PMID 26784231, 2016). "High-dose (HD) interleukin-2 (IL-2), a cytokine-based immunotherapy, was the first immunotherapy to be used for patients with metastatic melanoma." (PMID 27598148, 2016). "Activation of T cells and natural killer (NK) cells both systemically and locally within the tumor microenvironment using cytokines such as interleukin-2 (IL-2) is one approach that has been used extensively against metastatic melanoma." (PMID 27153543, 2016). "High-dose interleukin-2 (HD IL-2) was approved for treatment of metastatic renal cell carcinoma (mRCC) in 1992 and for metastatic melanoma (mM) in 1998, in an era predating targeted therapies and immune checkpoint inhibitors." (PMID 27714434, 2016). "Prior to 2010, the systemic treatment of choice for advanced metastatic melanoma was limited to cytotoxic chemotherapy and traditional forms of immunotherapy (interleukin-2, IL-2; interferon α-2b, IFN α-2b)." (PMID 27833586, 2016).
metastatic melanoma (continued). "There are several ongoing clinical trials testing HD IL2 in combination with newer agents in patients with metastatic melanoma and RCC." (PMID 26799322, 2016). "Taken together, these findings indicate that, although STAT5 activation is normal in metastatic melanoma patients in response to IL-2, indirect STAT1 activation is defective owing to deficiencies in the NK cell response to IL-2." (PMID 27153543, 2016). "High dose (HD) IL-2 therapy has been used for almost two decades as an immunotherapy for metastatic melanoma." (PMID 27153543, 2016). "Our findings are consistent with the reports on the efficacy of AIT in patients with metastatic melanoma using TILs grown in IL-2." (PMID 26928306, 2016). "Taken together, our data suggest that an impaired IFN-γ secretion by NK cells was responsible for the defective STAT1 activation in NK and T lymphocytes from metastatic melanoma patient in response to IL-2." (PMID 27153543, 2016). "The administration of high-dose intravenous interleukin-2 (IL-2) for metastatic renal cell carcinoma and metastatic melanoma was first approved by the US Food and Drug Administration (FDA) in 1992 and 1998, respectively." (PMID 26557408, 2015). "In metastatic melanoma or renal cell carcinoma, a similar concept of stereotactic body radiation therapy followed by high-dose IL-2 has shown promising clinical responses in 8 out of 12 patients." (PMID 25622640, 2015). "Interleukin-2 (IL-2) was the first immunotherapy to be approved for metastatic melanoma (1998) and was approved on the basis of long-lasting complete response." (PMID 26420268, 2015). "There are several FDA approved therapies currently on the market that make use of IL-2 to fight metastatic melanoma and renal cell carcinoma." (PMID 26255627, 2015). "We retrospectively analyzed clinical variables and biomarkers of 50 consecutive metastatic melanoma or renal cell carcinoma patients treated at our institution with IL-2 during 2004 – 2012." (PMID 25815245, 2015). "There are currently 60 institutions in North America that administer high-dose IL-2 therapy for metastatic melanoma and renal cell carcinoma." (PMID 26557408, 2015). "Our data reported here adds additional support to further clinical studies of combination IL-2 and ipilimumab in patients with metastatic melanoma." (PMID 25992289, 2015). "Immunotherapy with IL-2 is already used in the clinics to treat patients with metastatic melanoma and renal cell carcinoma with objective clinical response rates of 15–25%." (PMID 26220086, 2015). "Another open-label, uncontrolled, two-arm, multi-center study has been designed to assess CR rate in BRAFV600 metastatic melanoma patients who have received vemurafenib plus HD IL-2 (NCT01683188)." (PMID 25709607, 2015). "T-cell transfer immunotherapy that uses tumor-infiltrating lymphocytes and high dose interleukin-2 has demonstrated durable, complete responses for many years in patients with metastatic melanoma." (PMID 25537510, 2015). "High-dose IL-2 (HDIL2) is an approved immunotherapy for patients with metastatic melanoma and renal cell carcinoma with durable objective responses observed in 17-20%." (PMID 24885155, 2014). "IL-2 is an immune stimulatory cytokine that activates T-cells by binding to its receptor and has been approved for clinical immunotherapy against metastatic melanoma." (PMID 25380524, 2014). "High-dose IL-2 (HDIL2) is approved for the treatment of metastatic melanoma and renal cell carcinoma, but its use is limited in part by toxicity related to the development of vascular leak syndrome (VLS)." (PMID 24885155, 2014). "The combination of a lymphodepleting preparative regimen with adoptive transfer of TILs and administration of IL-2 has been shown to promote cancer regression in patients with metastatic melanoma, leukemias, and other types of tumor." (PMID 24860566, 2014).
metastatic melanoma (continued). "The IL-2 pathway is a key component of the immune response against infections but has been shown to be effective in certain cancers such as metastatic melanoma." (PMID 24304444, 2014). "One interesting small trial combined high-dose IL-2 with ipilimumab in 36 patients with metastatic melanoma." (PMID 24743024, 2014). "In a randomized clinical trial for metastatic melanoma patients, IL-2 combined with a gp100 peptide vaccine doubled the clinical responses compared to those patients receiving IL-2 alone." (PMID 24743024, 2014). "High dose interleukin-2 remains an important component of the therapeutic armamentarium for patients with metastatic renal cell cancer and metastatic melanoma." (PMID 31546315, 2014). "High-dose interleukin-2 (HD-IL-2) bolus has been shown to obtain objective response rates ranging from 15% to 17% in patients with metastatic melanoma or renal cell carcinoma (RCC), with 6% to 8% of cases experiencing a durable complete response." (PMID 25245327, 2014). "High-dose IL-2 is used for the treatment of patients with metastatic melanoma and metastatic renal cell carcinoma, and has a long-term impact on overall survival." (PMID 23294527, 2013). "High-dose interleukin-2 (HD IL-2) therapy was FDA approved for the treatment of metastatic melanoma in 1998." (PMID 23762555, 2013). "IL-2 therapy can be effective in the treatment of patients with metastatic renal cell carcinoma and metastatic melanoma." (PMID 23294527, 2013). "Today, the adoptive transfer of tumor-infiltrating lymphocytes combined with total-body irradiation, lymphodepleting chemotherapy, and high-dose IL-2 achieve response rates as high as 70% in patients with metastatic melanoma." (PMID 24098300, 2013). "Given the available data, interleukin 2, ipilimumab and verurafenib should be considered in each patient with metastatic melanoma." (PMID 29147288, 2012). "Unfractionated polyclonal TILs, after ex vivo expansion, have been used to treat patients with metastatic melanoma, in conjunction with systemic recombinant IL2." (PMID 22778760, 2012). "FDA-approved treatments for metastatic melanoma including IL-2, chemotherapy, ipilimumab, and vemurafenib have variable response rates and rarely result in durable complete responses." (PMID 22726267, 2012). "Immunotherapy with high-dose interleukin-2 (HDIL-2) is an effective treatment for patients with metastatic melanoma and renal cell carcinoma." (PMID 22532866, 2012). "High-dose IL-2 was approved by the FDA for the treatment of metastatic melanoma in January 1998 due to its ability to mediate durable responses." (PMID 22333219, 2012). "Like TNF-alpha, IL2 is also added exogenously to treat multiple cancer types including metastatic melanoma and superficial bladder tumors." (PMID 22536907, 2012). "These included approval of dacarbazine in 1975 for metastatic melanoma, approval of high dose interferon in 1995 for adjuvant therapy, and approval of high dose interleukin-2 in 1998 for treatment of metastatic melanoma." (PMID 29147288, 2012). "Approved treatments for metastatic melanoma include high-dose interleukin-2 (IL-2) and chemotherapy, which have, at best, an overall response rate of 16% and 7.5%, with very few complete responders and almost no long-term survivors." (PMID 23189169, 2012). "For example, administration of IL-2 causes transient lymphocytosis (increased ALC), which correlates with tumor response in metastatic melanoma and renal cancer." (PMID 22369276, 2012). "The intravenous administration of high-dose interleukin-2 (IL-2) constitutes an effective treatment for patients with metastatic melanoma and the treatment capable of providing long-term complete responses and potential cure in these patients." (PMID 22333219, 2012). "In Denmark systemic treatment with high dose Interleukin 2/Interferon (IL-2/IFN – Keilholz decrescendo regime) is 1st line treatment for patients with metastatic malignant melanoma." (PMID 22539948, 2012).
metastatic melanoma (continued). "In a prior study, we examined the effect of DAB/IL2 on the peripheral blood concentration of Treg cells in 16 metastatic melanoma patients." (PMID 22165955, 2011). "Some of the first trials demonstrating the potential of immunotherapy in cancer used high-dose interleukin-2 (IL-2) in patients with metastatic melanoma and renal cell carcinoma." (PMID 21331153, 2011). "IL-2 plays a pivotal role in the treatment of patients with metastatic melanoma and renal cell carcinoma." (PMID 24213115, 2011). "The Cytokine Working Group conducted a study of high-dose IL-2 plus an HLA-A2-restricted gp-100 peptide in HLA-A2-positive patients with metastatic melanoma." (PMID 24213115, 2011). "The potential of cytokines in the field of cancer immunotherapy is best exemplified by high dose IL-2, which can induce durable complete responses in a subset of metastatic melanoma and renal cell carcinoma patients." (PMID 24213115, 2011). "Specific human leukocyte antigen (HLA) classes I and II antigens have been associated with greater response to therapy and OS in patients with metastatic melanoma treated with interleukin-2." (PMID 22220281, 2011). "Current treatment options for patients with metastatic melanoma include several immunotherapeutic agents, such as high dose interleukin 2 (IL-2), interferon (IFN) α-2b and ipilimumab (an anti-cytotoxic T lymphocyte antigen-4 [CTLA4] antibody)." (PMID 22165955, 2011). "From 2003 to 2009, 24 metastatic melanoma patients were treated with mature dendritic cells pulsed with autologous tumor lysate and keyhole limpet hemocyanin and low-dose interleukin-2." (PMID 20936106, 2010). "Up to now, the best results for patients with metastatic melanoma have been obtained with adoptive therapy involving lymphodepletion followed by the intravenous injection of exvivo expanded TIL plus IL2." (PMID 20953324, 2010). "The most widely used immunomodulating drugs in metastatic melanoma are Interleukin 2 (IL-2) and Interferon α (IFN-α)." (PMID 24281101, 2010). "In a study of 59 patients with metastatic melanoma or renal cell carcinoma receiving high dose recombinant interleukin-2 (IL-2), serum was collected and analyzed for potential biomarkers of response using a customized protein array platform." (PMID 20178639, 2010). "Despite these setbacks, intravenously administered IL-2 endures as an FDA approved immunotherapeutic treatment option for patients with metastatic melanoma or renal cell carcinoma." (PMID 20936120, 2010). "In 1994, Rosenberg and colleagues demonstrated the utility of adoptive cellular therapy in metastatic melanoma patients by transfer of autologous TILs in combination with high-dose IL-2." (PMID 20936120, 2010). "High dose IL2 induces tumor response rates of approximately 15% in patients with metastatic melanoma, with nearly half of these responses being extremely durable and leading to a seemingly cured subset of patients." (PMID 19640287, 2009). "The treatment options for patients with metastatic melanoma are limited to palliation or to aggressive therapy with high dose IL-2 or biochemotherapy using cisplatin, vinblastine, dacarbazine, IL-2 and interferon α-2b." (PMID 18334033, 2008). "We administered DAB/IL2 (12 μg/kg; four daily doses; 21 day cycles) to 16 patients with metastatic melanoma and measured the effects on the peripheral blood concentration of several T cell subsets and on tumor burden." (PMID 18334033, 2008). "PBMC from an HLA-A2+ patient with metastatic melanoma are used to establish 96 independent microcultures which are sensitized for 10 days with 1 uM of gp100154–162 in the presence of IL-2 (90 IU/ml)." (PMID 18937837, 2008). "What is the role of single-agent interleukin-2 (il-2) in the treatment of adults with metastatic melanoma?" (PMID 17576460, 2007).